MTAP (methylthioadenosine phosphorylase)
Diseases named in the same sentence as MTAP in open-access papers (continued):
Sharing a sentence is not in itself a finding about the gene and the disease.
myxofibrosarcoma (2 papers, 2014 to 2020). A malignant fibroblastic neoplasm arising from the soft tissue. "Analogously, MMP-9 overexpression in the ASS1-deficient and MTAP-deficient myxofibrosarcomas is likely mediated by overexpressed ODC, which converges growth-promoting signals to orchestrate transcriptional regulation." (PMID 25426549, 2014). "Clinically, the independent effect of MTAP deficiency on adverse MFS in myxofibrosarcomas was reflective of these MTAP-associated antimigratory and antiinvasive functions." (PMID 25426549, 2014). "In conclusion, homozygous deletion primarily accounts for the adverse prognostic impact of MTAP deficiency and confers the biological aggressiveness and susceptibility to L-alanosine in myxofibrosarcomas." (PMID 25426549, 2014). "According to matrigel invasion assays, the 2 conditions also yielded significantly increased invading tumor cells, indicating enhanced metastatic propensity by MTAP deficiency in myxofibrosarcomas." (PMID 25426549, 2014). "In this study, MTAP protein deficiency in myxofibrosarcomas was associated with a poor prognosis and inactivated MTAP gene, caused by either homozygous deletion or promoter methylation." (PMID 25426549, 2014). "In summary, MTAP deficiency in myxofibrosarcomas, and particularly that caused by homozygous deletion, negatively affects prognosis." (PMID 25426549, 2014). "In the MTAP-deficient xenografts and myxofibrosarcoma specimens, MMP-9 overexpression was present in the tumor cells and extracellular stroma and associated with increased microvessel density." (PMID 25426549, 2014). "This approach significantly reverted the attenuated cell viability caused by L-alanosine, indicating that its antitumor selectivity was attributable to the MTAP deficiency in myxofibrosarcoma cells." (PMID 25426549, 2014). "Given the clinical relevance of MTAP deficiency in myxofibrosarcomas, we characterized the biology of MTAP expression to clarify its functional effects on cancer hallmark-related phenotypes." (PMID 25426549, 2014). "The MTAP immunostain of 87 independent primary myxofibrosarcomas demonstrated an aberrant MTAP deficiency in 32 cases (37%)." (PMID 25426549, 2014). "By restricting the adenosine monophosphate (AMP) supply, L-alanosine induced prominent apoptosis in the MTAP-deficient myxofibrosarcoma cells and derived xenografts." (PMID 25426549, 2014). "We applied MTAP reexpression or knockdown to elucidate the functional roles of MTAP and the therapeutic potential of L-alanosine in MTAP-preserved and MTAP-deficient myxofibrosarcoma cell lines and xenografts." (PMID 25426549, 2014). "Stable MTAP-reexpressing OH931 and NMFH-2 cells were employed to explore how MTAP expression affected the susceptibility of myxofibrosarcoma cells to L-alanosine." (PMID 25426549, 2014). "In addition, we demonstrated that myxofibrosarcomas fundamentally depended on MTAP deficiency regarding their susceptibility to L-alanosine, which effectively inhibited the MTAP-deficient cell lines and derived xenografts and was well-tolerated by the mice." (PMID 25426549, 2014). "By integrating various methodologies, we identified the clinical, biological, and therapeutic relevance of MTAP deficiency, which was observed in 37% of primary myxofibrosarcomas, strongly linked to homozygous deletion or promoter methylation, and independently predictive of adverse survival." (PMID 25426549, 2014). "All myxofibrosarcoma cell lines were incubated with indicated doses of L-alanosine for 72 h; this attenuated the cell viability in only the MTAP-deficient parent NMFH-2 and OH931 cells yielding IC50 values of approximately 1 μM and 5 μM, respectively, but not in the MTAP-expressing NMFH-1 cells." (PMID 25426549, 2014). "Functionally, MTAP deficiency yielded increased aggression in myxofibrosarcoma cells." (PMID 25426549, 2014).
myxofibrosarcoma (continued). "Because L-alanosine can completely abrogate AMP supply in MTAP-deficient cells, we investigated whether L-alanosine can effectively inhibit this aggressive subset of myxofibrosarcomas by targeting the methionine de novo pathway." (PMID 25426549, 2014). "Since several antimetabolites targeting purine synthesis are available and additional drugs are in development, the findings of this study suggest that MTAP-deficient myxofibrosarcomas may benefit from the chemoselective targeting of the defects in methionine-adenine recycling and AMP synthesis." (PMID 25426549, 2014). "In vitro and in vivo, MTAP may act as a tumor suppressor, serving antiangiogenic, antiproliferative, and antimigratory or antiinvasive functions, and its deficiency represents a potential therapeutic target of myxofibrosarcomas." (PMID 25426549, 2014). "To elucidate the potential MTAP-associated antitumor function, we compared the BrdU readout of myxofibrosarcoma cells engineered to manifest various MTAP expression levels." (PMID 25426549, 2014). "Regarding various mechanisms regulating MTAP expression, MTAP-homozygously deleted myxofibrosarcomas behaved aggressively and exhibited significantly shorter DSS (P = 0.0129) and MFS (P = 0.0150) values than did the cases lacking homozygous deletion." (PMID 25426549, 2014). "We first characterized myxofibrosarcoma cell lines regarding their MTAP gene status and endogenous protein expression." (PMID 25426549, 2014). "Real-time RT-PCR showed decreased expression of MMP-9 mRNA in both MTAP-reexpressing myxofibrosarcoma cell lines." (PMID 25426549, 2014). "Collectively, the mechanistic and clinical evidence reinforces MTAP as a functional tumor suppressor gene exhibiting prognostic and therapeutic relevance in myxofibrosarcomas." (PMID 25426549, 2014). "Under various experimental conditions used to manipulate MTAP expression, 3 myxofibrosarcoma cell lines were assessed for the formation of HUVEC tubes incubated with corresponding conditioned media." (PMID 25426549, 2014). "Collectively, these findings corroborated endogenous MTAP as a functional suppressor that governs myxofibrosarcoma pathogenesis by inhibiting tumor proliferation, metastasis, and angiogenesis." (PMID 25426549, 2014). "In MTAP-reexpressing and shLacZ-transduced myxofibrosarcoma cells, angiogenic capability was significantly impaired, as indicated by reduced levels of HUVEC-derived tube formation." (PMID 25426549, 2014). "Compared with the equally indolent MTAP-hypermethylated and MTAP-expressing myxofibrosarcomas, MTAP-homozygously deleted tumors were often high-grade and clinically aggressive." (PMID 25426549, 2014). "In the MTAP-reexpressing NMFH-2 myxofibrosarcoma transfectants, the readout indicative of cell proliferation significantly reduced, whereas shMTAP effectively promoted cell proliferation in the NMFH-1 cells exhibiting endogenous MTAP." (PMID 25426549, 2014). "The disabled methionine salvage in MTAP-inactivated myxofibrosarcomas renders this aggressive tumor subset a tumor-specific metabolic feature for use in L-alanosine therapy, which targets adenylosuccinate synthetase to abolish de novo AMP synthesis from IMP." (PMID 25426549, 2014). "Therefore, we applied MATP-bearing vectors and shMTAP to decipher how inactivated MTAP modulates myxofibrosarcoma phenotypes regarding various cancer hallmarks." (PMID 25426549, 2014). "In vitro and in vivo, the growth inhibition of MTAP-deficient tumors by L-alanosine was partially ascribed to the induction of apoptosis, which was evidenced by increased Annexin-V and TUNEL labeling in myxofibrosarcomas and reported to be mitochondria-dependent in mantle cell lymphomas." (PMID 25426549, 2014). "In the luciferase reporter assay, the antiangiogenic effect of MTAP was determined to primarily link to the transcriptional repression of MMP-9, ultimately attenuating mRNA and protein expression in the myxofibrosarcoma cells." (PMID 25426549, 2014).
myxofibrosarcoma (continued). "More recent studies have demonstrated a non-random loss of chromosome 9, with deletion of the methylthioadenosine phosphorylase (MTAP) and CDKN2A/CDKN2B genes (9q21.3) associated with increased aggressiveness in myxofibrosarcoma." (PMID 31722230, 2020). "However, MTAP homozygous deletion represents a relatively late genetic event in the tumor progression, which may confer survival advantage to aggressive subclones of myxofibrosarcoma cells and thereby culminate in negative prognostic impact." (PMID 25426549, 2014).
neuroblastoma (2 papers, 2022 to 2024). Neuroblastoma (NB) is the most common solid, extracranial childhood tumor. "However, MTAP lesions have not been shown in neuroblastoma – in fact MTAP has been reported to be transactivated by MYCN." (PMID 39313128, 2024).
oligodendroglioma (2 papers, 2024). A well-differentiated (WHO grade II), diffusely infiltrating neuroglial tumor, typically located in the cerebral hemispheres. "In the oligodendroglioma group, MTAP loss was detected in 7 (9.9%) of 73 tumors evaluated." (PMID 38109891, 2024). "In the oligodendrogliomas, the sensitivity of MTAP for the first observer was 80%, and the specificity was 95.45%, while the sensitivity for the second observer was 100%, and the specificity was 96.97%." (PMID 38109891, 2024).
oral squamous cell carcinoma (2 papers, 2009 to 2024). "The deletions of 9p22 containing IFNA and 9p21 containing MTAP and p16 genes and 9p allelic losses were also observed in oral squamous cell carcinoma." (PMID 19622142, 2009).
peritoneal mesothelioma (2 papers, 2022 to 2025). A benign or malignant mesothelial neoplasm that arises from the peritoneum. "Larger, multicentric studies are needed to validate the diagnostic role of MTAP IHC in peritoneal mesothelioma." (PMID 40566743, 2025). "MTAP immunohistochemistry (IHC) was evaluated as a diagnostic tool for peritoneal mesothelioma by comparing it with CDKN2A homozygous deletion (HD) detected by FISH." (PMID 40566743, 2025). "Our study represents the first formal evaluation of the reliability of MTAP IHC as a surrogate of CDKN2A FISH in a cohort of only peritoneal mesothelioma." (PMID 40566743, 2025). "The aim of our study was to evaluate the reliability of MTAP IHC as a surrogate marker for CDKN2A HD in peritoneal mesothelioma." (PMID 40566743, 2025). "The receiver operating characteristic (ROC) curve confirmed the results obtained in the first concordance analyses with Cohen's Kappa, proving that MTAP IHC is not informative for the status of CDKN2A copy number in our peritoneal mesothelioma cases." (PMID 40566743, 2025). "Results showed low concordance between MTAP IHC and CDKN2A HD, suggesting MTAP IHC is not reliable for predicting CDKN2A HD in peritoneal mesothelioma." (PMID 40566743, 2025).
pilocytic astrocytoma (2 papers, 2016 to 2020). Pilocytic astrocytoma is a rare subtype of low-grade glioma of the central nervous system characterized by a well circumscribed, often cystic, brain tumor with a discrete mural nodule and long, hair-like projections that extend from the neoplastic astrocytes. "We previously reported that MTAP loss occurs in less than 15% of pilocytic astrocytomas (WHO grade I)." (PMID 32093414, 2020).
Pleural effusion (2 papers, 2018 to 2023). The presence of an excessive amount of fluid in the pleural cavity. "The introduction of BAP1, MTAP and p16 tests has greatly improved the diagnostic accuracy of pleural effusions, but it is necessary to perform at least two of these tests (i.e., BAP1 and MTAP) to reach a good sensitivity." (PMID 38067238, 2023). "In this prospective cohort, we also confirmed the usefulness of BAP1 and MTAP IHC tests on pleural effusions, whose combination reached excellent diagnostic accuracy." (PMID 38067238, 2023). "Recent studies have investigated the use of methylthioadenosine phosphorylase (MTAP) IHC in combination with BAP1 to distinguish benign from malignant mesothelial proliferations, particularly from pleural effusion samples." (PMID 30060501, 2018).
alcoholic liver diseases (1 paper, 2013). A disorder caused by damage to the liver parenchyma due to alcohol consumption. "First, we analyzed hepatic tissue from patients with alcoholic liver disease and chronic viral infection and found significant lower MTAP mRNA and protein expression in liver cirrhosis compared to normal liver tissue." (PMID 24324622, 2013).
anaplastic meningioma (1 paper, 2025). A WHO grade III meningioma characterized by the presence of malignant morphologic features, including malignant cytology and a very high mitotic index (20 or more mitoses per ten high power fields). "Our results suggest that MTAP IHC can be unreliable as a sole surrogate for CDKN2A loss in anaplastic meningioma." (PMID 40227557, 2025). "This study analyzed the concordance between molecular methods - DNA methylation profiling, molecular inversion probe (MIP) analysis, targeted next-generation sequencing (NGS), and fluorescence in situ hybridization (FISH) - and protein expression of p16 and MTAP in nine anaplastic meningiomas." (PMID 40227557, 2025).
astrocytic tumor (1 paper, 2023). A glial tumor of the brain or spinal cord showing astrocytic differentiation. "The utility of methylthioadenosine phosphorylase (MTAP) IHC as a surrogate marker of CDKN2A HD in astrocytic tumors has been demonstrated, as has been that of p16 IHC in a few EPN-ZFTA cases." (PMID 37322295, 2023).
cardiac hypertrophy (1 paper, 2022). "Also the following tachycardia-specific miR-1183-regulated targets showed a cardiovascular association: the gene NEU3 with cardiac fibrosis and CHD, ZNRD1 with CHD, TRIM16 with cardiac hypertrophy, BIRC3 with ischemic preconditioning, ARRDC3 with cardiac hypertrophy, and MTAP with ischemic stroke." (PMID 35805966, 2022).
Cirrhosis (1 paper, 2013). A chronic disorder of the liver in which liver tissue becomes scarred and is partially replaced by regenerative nodules and fibrotic tissue resulting in loss of liver function. "Similar as in human cirrhosis, MTAP mRNA and protein expression were significantly reduced in the BDL model." (PMID 24324622, 2013). "Hepatic fibrosis and cirrhosis are HCC preconditions, and we have shown downregulation and tumor suppressor activity of MTAP in HCC." (PMID 24324622, 2013).
colorectal tumors (1 paper, 2024). "As the majority of human tumors are MTAP+/+, including approximately 98% of colorectal tumors, MTDIA can be an effective strategy for sensitizing them to MAT2a inhibitors." (PMID 38000655, 2024).
diffuse malignant peritoneal mesothelioma (1 paper, 2023). "Further, it was shown that loss of 5-hmC can be an additional valuable marker, alongside BAP1 and MTAP immunostains, for distinguishing diffuse malignant peritoneal mesothelioma from reactive mesothelial hyperplasia in peritoneal biopsies." (PMID 37834158, 2023).
dilated cardiomyopathy (1 paper, 2025). Cardiomyopathy which is characterized by dilation and contractile dysfunction of the left and right ventricles. "Assessment of single-nucleus RNA-seq from human hearts 65—including non-failing (NF), hypertrophic cardiomyopathy (HCM), and dilated cardiomyopathy (DCM) samples—suggests that compared to other 9p21.3 genes, MTAP showed the highest expression levels across all cardiac cell types." (PMID 41332607, 2025).
ductal adenocarcinomas (1 paper, 2025). "This number is somewhat higher than the 29.7% in our previous study analyzing a subset of 531 of our 769 primary ductal adenocarcinomas in a comparative evaluation of 149 different tumor entities for MTAP deficiency." (PMID 40227771, 2025). "In this study, intratumoral heterogeneity of MTAP deficiency was thus assessed in more than 200 ductal adenocarcinomas of the pancreas in a tissue microarray format and whole-section analysis was carried out by immunohistochemistry and fluorescence in situ hybridization." (PMID 40227771, 2025). "The near-perfect correlation between MTAP deficiency by IHC and homozygous deletion by FISH confirms the assay quality and characterizes ductal adenocarcinomas of the pancreas as a tumor entity where MTAP deficiency is always caused by deletion." (PMID 40227771, 2025).
ependymal tumor (1 paper, 2023). A group of neoplasms which arise from the ependymal lining of the cerebral ventricles and from the remnants of the central canal of the spinal cord. "The relationship between the CDKN2A hemizygous deletion and the expression of MTAP or p16 has not yet been reported for ependymal tumors." (PMID 37322295, 2023).
epithelioid mesothelioma (1 paper, 2022). "Demonstration of loss of BAP1 or MTAP by immunohistochemistry, or CDKN2A homozygous deletion by FISH, is valuable in establishing the diagnosis of epithelioid mesothelioma." (PMID 36552912, 2022).
Familial adenomatous polyposis (1 paper, 2021). Familial adenomatous polyposis (FAP) is characterized by the development of hundreds to thousands of adenomas in the rectum and colon during the second decade of life. "A mouse model of human Familial Adenomatous Polyposis responds favorably to pharmacological inhibition of 5′-methylthioadenosine phosphorylase (MTAP)." (PMID 33893330, 2021).
Fanconi anemia (1 paper, 2025). Fanconi anemia (FA) is a hereditary DNA repair disorder characterized by progressive pancytopenia with bone marrow failure, variable congenital malformations and predisposition to develop hematological or solid tumors. "Methylthioadenosine phosphorylase (MTAP) deficiency in tumor cells reduces the expression of Fanconi anemia (FA) genes, critical for repairing interstrand cross-link (ICL)-induced DNA damage." (PMID 40565099, 2025).
gastric adenocarcinoma (1 paper, 2026). "MTAP loss proved to be an independent factor for worse overall survival in patients with gastric adenocarcinoma." (PMID 42129334, 2026).
Hepatic fibrosis (1 paper, 2013). The presence of excessive fibrous connective tissue in the liver. "MTAP and MTAP modulating mechanisms appear as promising prognostic markers and therapeutic targets for hepatic fibrosis." (PMID 24324622, 2013).
histiocytic sarcoma (1 paper, 2015). An aggressive malignant neoplasm with a poor response to therapy, usually presenting as stage III/IV disease. "Focal deletions involving the MTAP and CDKN2A/B loci on CFA 11q16 are among the most highly recurrent somatic CNAs in a broad range of naturally occurring canine cancers, including appendicular osteosarcoma, histiocytic sarcoma, and non-Hodgkin’s lymphoma." (PMID 25957863, 2015).
intrahepatic cholangiocarcinoma (1 paper, 2024). A carcinoma that arises from the intrahepatic bile duct epithelium in any site of the intrahepatic biliary tree. "MTAP-loss tumors were more prevalent in East Asian patients with PDAC (4.4% vs 3.2%, P = .005) or intrahepatic cholangiocarcinoma (IHCC; 6.4% vs 4.3%, P = .036)." (PMID 38330461, 2024).
kidney cancer (1 paper, 2019). Primary or metastatic malignant neoplasm involving the kidney. "Because of the inverse correlation between MTAP expression and RCC progression, we hypothesized that the metabolic enzyme MTAP plays an inhibitory role in the aggressive nature of kidney cancer." (PMID 30701095, 2019).
Lewis lung carcinoma (1 paper, 2025). "To assess the role of MTAP in regulating antitumor immunity, we employed an immunocompetent murine model using Lewis lung carcinoma (LLC) cells with or without MTAP expression." (PMID 41246302, 2025).
liver cancer (1 paper, 2014). An epithelial or non-epithelial malignant neoplasm that arises from the liver. "Using TargetScan and miRanda database, we found that the potential predicated target genes of miR-646 consist of methylthioadenosine phosphorylase (MTAP), WEE1 G2 checkpoint kinase (WEE1), and cyclin D2 (CCND2), which are involved in the development of liver cancer." (PMID 25177719, 2014).